FAH (fumarylacetoacetate hydrolase)
Diseases named in the same sentence as FAH in open-access papers (continued):
Sharing a sentence is not in itself a finding about the gene and the disease.
hepatocellular carcinoma (13 papers, 2016 to 2025). A malignant tumor that arises from hepatocytes. "One of the most interesting findings of this study was the disclosure of rare germline damaging variants affecting genes linked to liver differentiation and function, such as FAH, that cause a recessive disorder related to hepatocellular carcinoma risk." (PMID 35495172, 2022). "We found that loss-of-function of FAH promoted hepatoma cell growth and migration in comparison with siRNA controls." (PMID 27469031, 2016). "The study further asserts that patients with HT-1 also face long-term risks for developing hepatocellular carcinoma due to a deficiency in FAH and, thereby, the accumulation of toxic metabolites, causing progressive liver and kidney damage and neurological crises." (PMID 39050308, 2024). "HT1 is caused by a deficiency of fumarylacetoacetate hydrolase (FAH) and leads to severe liver disease, including acute liver failure, cirrhosis, and hepatocellular carcinoma." (PMID 38535121, 2024). "The downregulation of tyrosine metabolism pathway-related genes (HPD, HGD, GSTZ1, and FAH) was observed in hepatocellular carcinoma and indicated poor prognosis; however, investigation of dysregulation of tyrosine metabolism pathways in OSCC is lacking." (PMID 34422810, 2021). "ALDH, MDH2 and CMPK exhibited increased expression in human hepatoma 7.5 cells (HUH7.5) infected with Hepatitis C virus (HCV) and FAH was decreased in HCV-associated carcinoma tissue." (PMID 28086865, 2017). "Pathogenic variants in FAH cause TYRSN1, which induces cirrhosis and can progress to hepatocellular carcinoma (HCC)." (PMID 27397503, 2016).
liver disease (10 papers, 2009 to 2025). "Hereditary Tyrosinemia Type-1 (HT1), an inherited error of metabolism caused by a mutation in the fumarylacetoacetate hydrolase gene, is associated with liver disease, severe morbidity, and early mortality." (PMID 40143050, 2025). "FAH encodes fumarylacetoacetate hydrolase, the terminal enzyme in tyrosine catabolism; although classically linked to hepatic disease, perturbations in amino acid metabolism and downstream oxidative stress could, in principle, influence valvular cell homeostasis." (PMID 41472124, 2025). "Hereditary tyrosinemia type 1 (HT1) is caused by deficiency of the final enzyme in Phe/Tyr catabolism pathway, fumarylacetoacetate hydrolase (FAH), and is characterized by progressive liver diseases with increased risk for HCC." (PMID 31267557, 2019). "Fumarylacetoacetate hydrolase (FAH)-deficient mice were lethally irradiated and reconstituted with wildtype bone marrow (BM) in order to correct liver disease." (PMID 24109514, 2013). "In the patient reported here, there was no advanced liver disease or generalised nodular transformation at the time of biopsy, so the measured residual FAH enzyme activity is considered a genuine residual activity (of about 5%)." (PMID 20003495, 2009).
Cirrhosis (8 papers, 2016 to 2024). A chronic disorder of the liver in which liver tissue becomes scarred and is partially replaced by regenerative nodules and fibrotic tissue resulting in loss of liver function. "Through WES we were able to identify a novel variant in FAH in a family with cirrhosis and a predisposition to HCC." (PMID 27397503, 2016). "Moreover, picrosirius red staining revealed mild fibrosis in the liver of FAH−/− rabbits but not in wild type, which is in agreement with Fah−/− mice but contrasts with the development of cirrhosis in FAH-deficient rats and pigs." (PMID 28053091, 2017). "FAH−/− rabbits did not develop cirrhosis in our study, although it is likely that varying the NTBC administration/withdrawal routine and allowing more chronic damage would induce it." (PMID 28053091, 2017).
acute liver failure (6 papers, 2016 to 2024). Rapid deterioration of liver function causing encephalopathy and coagulopathy. "An alternate to the induction of hepatotoxicity by uPA transgene expression is genetic ablation of fumarylacetoacetate hydrolase (FAH) in mice resulting in acute liver failure which can be rescued by administration of the drug, 2-(2-nitro-4-fluoromethlbenzoyl)-1,-3-cyclohexanedione (NTBC)." (PMID 29725334, 2018).
liver cancer (6 papers, 2015 to 2022). An epithelial or non-epithelial malignant neoplasm that arises from the liver. "Finally, a LoF variant was identified in the DNA repair gene ERCC5, in which homozygous mutations increase the skin cancer risk, and a damaging missense variant was mapped to FAH and causes an autosomal-recessive disorder characterized by progressive liver disease with increased liver cancer risk." (PMID 35495172, 2022). "In this study, we demonstrated that the FAH protein level is elevated in liver cancer tissues compared to that in normal tissues." (PMID 33218190, 2020). "Our results showed that out of 26 liver cancer patients, 14 patients showed significantly high expression of FAH in tumor tissues when compared to the normal tissues." (PMID 33218190, 2020). "We selected 14 translated tumor-mutated alleles for validation using SRM, including three genes (i.e., HNF1A, FAH and SPTBN1) that have been causally related to liver cancer." (PMID 26631547, 2015). "Previous studies also showed that genes from tyrosine metabolism reprogramming (TAT, HPD, HGD, GSTZ1, and FAH) may be used as prognostic biomarkers in liver cancer." (PMID 35847355, 2022). "Furthermore, Immunohistochemistry (IHC) staining for FAH in liver cancer tissues showed very high expression levels in most of the cancer patients when compared with normal tissues." (PMID 33218190, 2020). "Thus, we wished to analyze the expression of FAH in liver cancer and normal tissues." (PMID 33218190, 2020).
viral infection (4 papers, 2017 to 2025). "Independently of STAT1, FAH was identified as a host factor that contributes to the control of viral infection, and its metabolite, DMF, exhibited antiviral activity." (PMID 40048440, 2025). "Furthermore, comprehensive functional screening identified fumarylacetoacetate hydrolase (FAH) as a previously unidentified candidate that contributes to the control of viral infection independently of STAT1." (PMID 40048440, 2025). "FAH was identified as a candidate host factor that contributes to the control of viral infection independent of STAT1, and its metabolite, DMF, exhibited antiviral activity." (PMID 40048440, 2025).
Immunodeficiency (3 papers, 2018 to 2024). Failure of the immune system to protect the body adequately from infection, due to the absence or insufficiency of some component process or substance. "The constructed FAH/RAG1/IL2RG triple-knockout pig models were characterized by chronic liver injury and severe immunodeficiency." (PMID 35255981, 2022).
melanoma (3 papers, 2017 to 2025). A malignant, usually aggressive tumor composed of atypical, neoplastic melanocytes. "We attribute the pro-tumoral actions of FAH to its ability to promote anaplerotic reactions that underlie metabolic reprogramming in melanoma cells." (PMID 29371990, 2017). "To model and test this association, we transduced human A375 and A875 melanoma cells with lentivirus expressing shRNA against FAH (shFAH) or scrambled (control) shRNA and then performed puromycin selection to establish stable clones." (PMID 29371990, 2017). "Meanwhile, Annexin V-FITC staining experiments showed that FAH knockdown was associated with increased apoptosis in the melanoma cell lines." (PMID 29371990, 2017). "We speculated that this phenomenon might be associated with sufficient endogenous FAH expression and limited substrates in melanoma cells." (PMID 29371990, 2017). "To investigate the impact of FAH fluctuations on melanoma cell growth and survival, we first knocked down FAH expression using two different siRNAs and analyzed proliferation, migration, apoptosis, and cell cycle staging." (PMID 29371990, 2017). "The present study offers novel insights into melanoma’s metabolic reprogramming, and suggests that FAH is both a useful independent prognostic biomarker and a relevant target for melanoma therapy." (PMID 29371990, 2017). "Subsequently, our in vitro studies using three human melanoma cell lines revealed that FAH regulates important biological processes such as proliferation, migration, and apoptosis." (PMID 29371990, 2017). "FAH knockdown inhibits proliferation and migration, while promoting apoptosis in melanoma cells, result in prolonged survival in tumor-bearing mice." (PMID 29371990, 2017). "Using immunodetection and clinical data analyses, we demonstrate here that fumarylacetoacetate hydrolase (FAH) is highly expressed in melanoma and correlates with poor survival." (PMID 29371990, 2017). "Analysis of a human melanoma tissue microarray by immunohistochemistry (IHC) with a FAH antibody revealed significantly higher, mainly cytosolic, FAH expression in melanoma than in benign nevus and normal skin." (PMID 29371990, 2017). "To shed light on the biological processes regulated by FAH, we performed mRNA expression profiling in control and FAH-knockdown melanoma cells." (PMID 29371990, 2017). "To further confirm that CDC5L increases FAH expression, we knocked down the Cdc5l gene in melanoma cells using two siRNAs, and analyzed FAH expression by real-time RT-PCR and western blot." (PMID 29371990, 2017). "Using bioinformatic, ChIP-PCR, and gene silencing analyses, we determined that cell division cycle 5-like protein (CDC5L) is an important transcription factor regulating FAH expression in melanoma cells." (PMID 29371990, 2017). "Thus, combined results from FAH silencing and overexpression experiments suggest that FAH promotes proliferation and migration, while inhibiting apoptosis in melanoma cells." (PMID 29371990, 2017). "In the present study, we evaluated FAH expression in clinical samples, conducted survival analyses in both patients’ data and a mouse melanoma model, and performed bioinformatics, real time RT-PCR, western blot and 13C tracing analyses to assess the role of FAH in human melanoma cells." (PMID 29371990, 2017). "In this study, we found that FAH is highly expressed in clinical specimens of melanoma, where it correlates with shortened survival times and may thus serve as an independent prognostic biomarker." (PMID 29371990, 2017). "Next, we increased the expression of FAH in melanoma cells using a plasmid vector (FAH-pcDNA3.1)." (PMID 29371990, 2017). "Whether FAH participates in anaplerotic reactions in melanoma cells remains unclear." (PMID 29371990, 2017). "In melanoma, CDC5L upregulates fumarylacetoacetate hydrolase (FAH) transcription, binds the proline-rich receptor-like protein kinase (PERK1) gene promoter, and activates the ERK1/2 and JAK2 pathways in ovarian cancer." (PMID 36012592, 2022).
melanoma (continued). "FAH-pcDNA3.1 transfection did not affect proliferation in melanoma cells but increased, as expected, their rate of migration compared with control cells." (PMID 29371990, 2017). "Our results indicate that FAH transcription, driven by cell division cycle 5-like protein (CDC5L), is essential in the metabolic reprogramming of melanoma by promoting important anaplerotic reactions that sustain tumor growth and potentiate the disease’s severity." (PMID 29371990, 2017). "Data showed that patients with high FAH levels exhibited significantly shortened OS and DFS than those in which FAH expression was low, suggesting the potential of FAH as an independent prognostic indicator for melanoma." (PMID 29371990, 2017). "In the melanoma cells studied here, both immunostaining and western blot showed that FAH localized mainly in the cytosol, rather than the mitochondria." (PMID 29371990, 2017).
glioma (2 papers, 2023 to 2024). A benign or malignant brain and spinal cord tumor that arises from glial cells (astrocytes, oligodendrocytes, ependymal cells). "Highly expressed tyrosine metabolizing enzymes 4‐hydroxyphenylpyruvate dioxygenase, homogentisate 1,2‐dioxygenase, and fumarylacetoacetate hydrolase not only promote the malignant phenotype of glioma but are also closely related to poor prognosis." (PMID 37786553, 2023). "In all, the highly expressed HPD, HGD, and FAH in glioma modulate the TME, alter the abundance of immune cells, and promote immune evasion." (PMID 37786553, 2023). "Taken together, these results suggest that the tyrosine metabolizing enzymes HPD, HGD, and FAH promote the malignant phenotype of glioma, which in turn exacerbates the poor prognosis of patients." (PMID 37786553, 2023). "On the other hand, tyrosine aminotransferase (TAT), HPD, HGD, and FAH were identified as unfavorable prognostic factors in glioma patients in the validation set." (PMID 37786553, 2023). "In addition, abnormal expression of tyrosine metabolizing enzymes (HPD, HGD, and FAH) alters the TME of glioma." (PMID 37786553, 2023). "Third, in glioma, increased protein levels of the tyrosine degradation pathway (HPD, HGD, and FAH) was correlated with higher PD-L1 expression, which promoted immune evasion by suppressing T-cell activity." (PMID 39592957, 2024). "In the CGGA database, the expressions of HPD, HGD, and FAH were significantly elevated in high‐grade glioma and IDH wild‐type glioma." (PMID 37786553, 2023). "To clarify the specific mechanism of tyrosine metabolizing enzymes regulating the malignant phenotype of glioma, we first calculated the optimal “cutpoint” using the R package algorithm and divided glioma patients into two groups according to the expression levels of HPD, HGD, and FAH." (PMID 37786553, 2023).
kidney damage (2 papers, 2016 to 2023). "In addition, these 106 potential classifiers/biomarkers between TCMR vs. STA are associated with kidney damage (e.g., ATP1B1, CST3, FAH, GSS, HPX and LYZ), tubule injury (e.g., CRYM, GSS, HAGH, HPX and LYZ) and kidney inflammation (e.g., DCN)." (PMID 36814924, 2023).
kidney failure (2 papers, 2022 to 2024). An acute or chronic condition that is characterized by the inability of the kidneys to adequately filter the blood. "HTI, the most clinically challenging of these disorders, is caused by mutations in the gene fumarylacetoacetate hydrolase (FAH) leading to the accumulation of toxic metabolites causing apoptosis and liver and renal failure." (PMID 36558364, 2022).
liver dysfunction (2 papers, 2015 to 2024). "HT1 is a rare genetic disorder caused by a deficiency in fumarylacetoacetate hydrolase (FAH), leading to the accumulation of toxic metabolites and subsequent liver dysfunction." (PMID 39707395, 2024).
MAAI deficiency (2 papers, 2024 to 2025). "We suggest that confirmatory testing after abnormal NBS for HT1 should include a work-up for MAAI deficiency in cases with a persistent—albeit slight—elevation of succinylacetone without the detection of biallelic pathogenic variants in the FAH gene." (PMID 38535121, 2024). "However, two additional conditions associated with DBS-SA elevation have been identified, namely partial FAH deficiency and maleylacetoacetate isomerase (MAAI) deficiency (MAAID)." (PMID 41009955, 2025).
phenylketonuria (2 papers, 2020 to 2022). Phenylketonuria (PKU) is the most common inborn error of amino acid metabolism and is characterized by mild to severe mental disability in untreated patients. "Diseases such as phenylketonuria (PKU) and hereditary tyrosinemia-I (HT1) are caused due to mutations in PAH and FAH gene, resulting in reduced protein stability, misfolding, accelerated degradation, and deficiency in functional proteins." (PMID 32679806, 2020).
steatosis (2 papers, 2016 to 2021). Increased lipid within the cytoplasm of cells. "Immunostaining for fumarylacetoacetate hydrolase (FAH) confirmed that steatosis was confined to human hepatocytes, repopulating across the whole liver acinus." (PMID 34036256, 2021).
bladder cancer (1 paper, 2024). "Unlike FAH and COL7A1, DICER1 has been directly investigated for its role in bladder cancer patients." (PMID 38580653, 2024).
breast carcinoma (1 paper, 2022). "We found that overexpression of fumarylacetoacetate hydrolase (FAH) in FRCs induced by breast cancer cells significantly increased mitochondrial OXPHOS levels and ATP production." (PMID 36266717, 2022).
cutaneous melanoma (1 paper, 2017). A primary melanoma arising from atypical melanocytes in the skin. "Then, we accessed the cBioPortal for Cancer Genomics to evaluate and correlate mRNA levels of FAH and the oxoglutarate/malate carrier SLC25A11 in cutaneous melanoma data from TCGA." (PMID 29371990, 2017).
Flavivirus Infections (1 paper, 2017). Infections with viruses of the genus FLAVIVIRUS, family FLAVIVIRIDAE. "Small molecule inhibitors of FAH and PARP are known but their potential to regulate flavivirus infection in arthropods has not been investigated." (PMID 28086865, 2017).
glioblastoma (1 paper, 2017). The most malignant astrocytic tumor (WHO grade IV). "A total of 5 key DNA repair genes, CDK7, DDB2, RNH1, RFC2 and FAH, were screened to be significantly related to the prognosis of glioblastomas (p = 9.74e−05)." (PMID 28938550, 2017).
hyperinsulinism (1 paper, 2020). Abnormally high levels of insulin in the blood. "Here, we report the case of an infant presenting with hyperinsulinism and developing multi-organ failure who harbored a novel homozygous pathogenic nonsense mutation in FAH (c.1014 delC; p.Cys 338 Ter) consistent with TT1." (PMID 32832707, 2020).
iritis (1 paper, 2017). Inflammation of the iris. "Using slit lamp imaging, we also noticed deeper chamber depth and lens opacification accompanied with dilated pupil and posterior synechia of the iris in the right eye of the first FAH+/− rabbit, implying cataract and iritis." (PMID 28053091, 2017).
kidney cancer (1 paper, 2015). Primary or metastatic malignant neoplasm involving the kidney. "From the unique set of genes detected by CANOVA, a few were reported to be relevant to kidney cancer/disease: FAH, MCM3 and UGT1A9." (PMID 26283601, 2015).
malignant glioma (1 paper, 2023). A grade III or grade IV glioma arising from the central nervous system. "In this study, based on the perspective of tyrosine metabolism, we found that the tyrosine metabolizing enzymes 4‐hydroxyphenylpyruvate dioxygenase (HPD), homogentisate 1,2‐dioxygenase (HGD), and fumarylacetoacetate hydrolase (FAH) were upregulated in more malignant glioma patients." (PMID 37786553, 2023).
tyrosinemia type II (1 paper, 2017). Tyrosinemia type 2 is an inborn error of tyrosine metabolism characterized by hypertyrosinemia with oculocutaneous manifestations and, in some cases, intellectual deficit. "As with tyrosinemia type II, corneal keratitis in HT1 patients and possibly FAH knock-out rabbits as well is caused by enhanced local accumulation of tyrosine, which is boosted by NTBC." (PMID 28053091, 2017).
metabolic disorder (11 papers, 2016 to 2025). "Hereditary tyrosinemia type I (HT-I) is an inherited metabolic disorder that results from a mutation in the Fah gene encoding fumarylacetoacetate hydrolase." (PMID 36833410, 2023). "Hereditary tyrosinemia type I (HTI) is a severe inherited metabolic disorder caused by loss-of-function mutation of FAH." (PMID 37051232, 2023). "Hereditary tyrosinemia (HT1) is a rare metabolic disorder associated with accumulation of toxic metabolites of the tyrosine pathway due to a genetically mediated enzyme defect of fumarylacetoacetate hydrolase." (PMID 33910593, 2021). "Hereditary tyrosinemia type I (HT1) is a metabolic disease caused by disruption of fumarylacetoacetate hydrolase (Fah), which is an enzyme required in the tyrosine catabolic pathway." (PMID 30604748, 2019). "Hereditary Tyrosinemia type 1 (HT1) is a rare metabolic disorder caused by a defect in the enzyme Fumarylacetoacetate Hydrolase." (PMID 27356512, 2016). "Knocking out hydroxyphenylpyruvate dioxygenase (HPD, an upstream enzyme of FAH) has been demonstrated to prevent toxic metabolite accumulation and has been used to treat HTI metabolic disease in Fah−/−mice." (PMID 37051232, 2023).